LEF1-AS1 (LEF1 antisense RNA 1)
Synonyms: LEF1NAT
Gene: Long non-coding RNA gene on chromosome 4 (108,167,332 to 108,305,657, forward strand). Ensembl gene ENSG00000232021.
Diseases named in the same sentence as LEF1-AS1 in open-access papers:
LEF1-AS1 is named in the same sentence as 3 diseases in open-access papers, as found by Europe PMC text mining. Sharing a sentence is not in itself a finding about the gene and the disease. The quoted sentences say what the papers report.
colorectal cancer (1 paper, 2021). A primary or metastatic malignant neoplasm that affects the colon or rectum. "LEF1 antisense RNA 1 (LEF1-AS1/LOC641518) is an antisense lncRNA encoded in the LEF1 locus, which is related to the metastasis in various tumors, including colorectal cancer and esophageal squamous cell carcinoma." (PMID 34256750, 2021).
LEF1-AS1 also shares sentences with these, for which no sentence is quoted: COVID-19 (1 paper); esophageal squamous cell carcinoma (1).